DUSP4 (dual specificity phosphatase 4)
Diseases named in the same sentence as DUSP4 in open-access papers (continued):
Sharing a sentence is not in itself a finding about the gene and the disease.
tumor (continued). "Similarly, we explored human proteomics databases incuding the Clinical Proteomic Tumor Analysis Consortium (CPTAC) to correlate the expression between ARID1A and DUSP4, as well as MAPK molecules." (PMID 38071325, 2023). "In this study, we found that DUSP4 knockout enhanced tumor growth in HCC xenograft nude mouse models without Lenvatinib treatment." (PMID 35864956, 2022). "In conclusion, we revealed that negative DUSP4 expression is associated with unfavorable clinicopathological characteristics (old age, high WHO/ISUP grade, tumor necrosis, and high pT category) in ccRCC patients." (PMID 34679636, 2021). "DUSP4, as well as cell adhesion molecule CEACAM6, was reduced in LA-treated cells as well, which could be a protective response against tumor progression." (PMID 33546321, 2021). "Negative DUSP4 expression was significantly associated with old age (p = 0.033), high WHO/ISUP grade (p < 0.001), presence of tumor necrosis (p < 0.001), and high pT category (p < 0.001)." (PMID 34679636, 2021). "Notably, some genes related to exhaustion were also overexpressed in tumor‐infiltrating Tregs including TYMS, KIAA0101, CXCL13, CD27, HLA‐DQB1, HLA‐DMA, ENTPD1, CD200, DUSP4, and ZBED2." (PMID 32659053, 2020). "We and others found that DUSPs are some of the most robustly regulated downstream targets of EGFR/ErbB2 signaling and indeed both DUSP4 and DUSP6 independently serve key modulatory functions and might be candidate tumor suppressor genes." (PMID 29861842, 2018). "DUSP4, also referred to as a mitogen-activated protein kinase phosphatase 2 (MKP-2), has been found to play a role in tumor suppression, regulation of mitogen-activated protein kinases (MAPKs), and cellular signal transduction from the cell surface to the nucleus." (PMID 28287479, 2017). "DUSP4 expression was significantly correlated with older age (P = 0.017), male gender (P = 0.036), larger tumor size (P = 0.014), nonmucinous tumor type (P = 0.023), and higher T stage (P = 0.040)." (PMID 25688264, 2015). "DUSP4 expression was significantly correlated with older age, male gender, larger tumor size, nonmucinous tumor type, and higher T stage." (PMID 25688264, 2015). "Five genes with tumor suppressing properties, i.e. SPRY4 (Sprouty homolog 4), DUSP4 and DUSP6 (dual-specificity phosphatases 4 and 6), LRIG1 (Leucine-rich repeats and Ig-like domains 1) and PHLDA1 (Pleckstrin homology-like domain family A, member 1), were upregulated by KGF (1.5–2.1 fold)." (PMID 22427941, 2012). "Of these, DUSP4 and DUSP6, PHLDA1 and Sprouty 4 are characterized by tumor suppressing properties." (PMID 22427941, 2012). "Whether DUSP4 and DUSP6 serve as oncogenes or tumour suppressors is still under debate." (PMID 37946160, 2023). "However, at the same time, it might be envisioned that DUSP4 and DUSP6 maintain pERK at tolerable levels allowing the tumour cells to reach a state of stemness to overcome proliferative insufficiency." (PMID 37946160, 2023). "As a result, short CSS was associated with negative DUSP4 expression (p = 0.018), high WHO/ISUP grade (p = 0.001), presence of tumor necrosis (p < 0.001), presence of sarcomatoid feature (p < 0.001), high pT category (p < 0.001), and presence of nodal metastasis (p < 0.001)." (PMID 34679636, 2021). "DUSP4 down-expression could promote the proliferation and survival of TNBC tumor cells." (PMID 32897241, 2020). "In addition, silence of DUSP4 could activate the Ras-ERK signaling pathway and further promote the proliferation and migration of tumor cells." (PMID 32742193, 2020). "Thus far the DUSP4−/− knockout mice have not been crossed into or utilised in any of the well-characterised murine cancer models and there is no direct evidence of a role for DUSP4/MKP-2 in the initiation or progression of tumours." (PMID 30401534, 2019). "Multivariate analysis showed that tumour size and AJCC stage were the risk factors for OS, while DUSP4 expression could not act as an independent prognostic factor for OS." (PMID 27957827, 2017).
tumor (continued). "Moreover, we observed a negative correlation with significance between G9a and DUSP4 in 20 HNSCC tumor specimens." (PMID 25027955, 2014). "Consequently, the impact of DUSP4 on diverse tumor types is not uniform." (PMID 40630642, 2025). "However, the role of Dusp4 in tumor initiation has not been studied." (PMID 35850776, 2022). "However, whether DUSP4 acts as a tumor promoter or tumor suppressor is still controversial and the consensus has not been reached on the exact role of DUSP4 expression in various human cancers." (PMID 25688264, 2015). "Tumor cells with fused genes showed overexpression of FOSB, FOS, and JUN, while tumor cells without fused genes overexpressed CXCR6 and DUSP4." (PMID 37736898, 2023). "In addition, negative DUSP4 expression (p = 0.012), high WHO/ISUP grade (p = 0.027), presence of tumor necrosis (p = 0.001), high pT category (p < 0.001), and presence of nodal metastasis (p < 0.001) were associated with short RFS." (PMID 34679636, 2021).
cancer (69 papers, 2010 to 2025). A tumor composed of atypical neoplastic, often pleomorphic cells that invade other tissues. "Cell proliferation assays, colony formation assays and cell migration assays were performed to investigate the effect of drug resistance associated genes, particularly DUSP4, on cancer cell malignant behavior during Lenvatinib treatment." (PMID 35864956, 2022). "In survival analysis, loss of DUSP4 expression was associated with poor clinical outcomes in cancer-specific survival and recurrence-free survival (p = 0.010 and p = 0.007, respectively)." (PMID 34679636, 2021). "A previous study showed that DUSP4 is widely expressed in different tissues and implicated in cancer development." (PMID 25027955, 2014). "Notably, ASCL2 and DUSP4 had the highest association with MSI in COAD compared to the other cancer types." (PMID 35774798, 2022). "In a study on renal carcinoma, it was shown that loss of DUSP4 expression could lead to a poor prognosis of the cancer." (PMID 35008796, 2021). "Importantly, DUSP4, a known cancer risk gene, is represented in both of these pathways, suggesting pleiotropy with multiple functional associations." (PMID 27788148, 2016). "Furthermore, the fact that DUSP4/MKP-2 has a proven role in immune regulation indicates that a conditionally targeted allele of DUSP4/MKP-2 would be required to avoid the confounding effects of deleting this MKP in immune cells on any cancer phenotypes observed." (PMID 30401534, 2019). "On the whole, DUSP4 plays an important role in cancer onset and progression, possibly with the exception of CRC." (PMID 40943262, 2025). "DUSP4 and DUSP6 are linked to MAPK signaling in cancers, and in our analysis, DUS4 and DUSP6 both appear on the Volcano and heat map, respectively." (PMID 39768125, 2024). "Given that CCA also shows DUSP4 upregulation in the presence of RAS mutations, we assume our observations can be extended to other cancer entities." (PMID 37946160, 2023). "i3 cancers showed higher expression of downstream MAPK components (DUSP4 and ETV5) and i2 cancers had overexpression of EGFR ligands, AREG and EREG." (PMID 35773407, 2022). "As a member of dual specificity phosphate (DUSP), DUSP4 was reported to participate in cancer development from several aspects." (PMID 36127345, 2022). "DUSP4 plays a complex role in oncogenesis, as reported in other cancers, and further work is required to fully understand its functional role in the MAPK pathway." (PMID 36576731, 2022). "The four genes are associated with important cancer pathways, namely, the MAPK/PI3K pathways (FN1 and DUSP4), the Wnt pathway (LEF1), and the TGF pathway (SMAD9)." (PMID 34485158, 2021). "In several types of cancer, DUSP4 expression affects carcinogenesis and drug resistance; thus, DUSP4 is considered a candidate prognostic marker or therapeutic target." (PMID 34679636, 2021). "Different studies have been conducted in several types of cancer, showing that DUSP4 has an oncogenic role, however others’ analysis have suggested a tumor suppressor activity." (PMID 35008796, 2021). "In ER-negative breast cancer cells, DUSP4 knockdown increases the formation of mammospheres and the expression of cancer stem cell promoting cytokines." (PMID 31936698, 2020). "In the clinical component, we also showed that the combination of ALDOA and TRAF4 or DUSP4 is positively correlated with poor overall survival in a xenograft model and cancer patients through immunohistochemical analyses." (PMID 32188842, 2020). "In cancers, DUSP4 expression is either up- or downregulated, and in GBM tissues, DUSP4 is generally downregulated." (PMID 30791455, 2019). "Mechanistically, this cancer appears to be dependent on JNK signalling for continued survival and loss of DUSP4/MKP-2 contributes to cancer progression by augmenting JNK activity." (PMID 30401534, 2019).
cancer (continued). "Because of its action as a negative regulator, reduced expression of Dusp4 causes aberrant MAPK activation; this pathway plays a critical role in the initiation and progression of cancer." (PMID 30086769, 2018). "Mean DUSP4 expression score was significantly higher in malignant tumors than in benign lesions (P < 0.001, Kruskal-Wallis test)." (PMID 25688264, 2015). "The role of dual-specificity protein phosphatase 4 (DUSP4) appears to vary with the type of malignant tumors and is still controversial." (PMID 25688264, 2015). "The exact role of DUSP4 in cancer development and progression appears to vary with the type of malignant tumors." (PMID 25688264, 2015). "DUSP4 was more frequently expressed in malignant tumors compared to that in benign lesions (P < 0.001)." (PMID 25688264, 2015). "Low levels of DUSP4/MKP-2 expression correlated with higher post neo-adjuvant chemotherapy cancer cell proliferation and a reduction in recurrence-free survival." (PMID 22812510, 2013). "Some of the upregulated genes are related to CSC/’cancer stemness’ such as CXCR4, CD133, EPCAM and SOX9, while others are associated with apoptosis (FASLG, TJP2, DUSP4), the MAPK pathway (MAP2K4, DUSP4), and chemoresistance (MMP1, an ETS1 target gene)." (PMID 24069258, 2013). "The higher expression of DUSP4 and TNC in co-cultured turtles indicated a lower risk of cancer." (PMID 38540060, 2024). "ARID1A-low group had significantly lower DUSP4 expression (p = 0.0125) in carcinoma tissues." (PMID 38071325, 2023). "Therefore, we determined the correlation between the expression of ASCL2 and DUSP4 with MSI in 32 cancer types." (PMID 35774798, 2022). "Therefore, for various cancers, DUSP4 is being considered as a therapeutic target or potential biomarker for predicting clinical outcomes." (PMID 34679636, 2021). "DUSP4 is considered a biomarker in various cancer studies, but its precise role is controversial." (PMID 34679636, 2021). "The DUSP4 gene is located at 8p12; according to data from TCGA’s Pan-Cancer Atlas studies, several genetic alterations have been identified in a small percentage (3.3%) of cancer cases." (PMID 34679636, 2021). "DUSP4 expression has been shown to be altered in a variety of human cancers." (PMID 29100381, 2017). "However, other studies indicate that overexpression of DUSP4 promotes cancer development and progression." (PMID 29212207, 2017). "Currently, the roles of DUSP4 in cancers remain controversial." (PMID 27957827, 2017). "Compared with normal tissues, there were two hypomethylation probes of DUSP4 in cancer tissues." (PMID 28500316, 2017). "In addition, loss of DUSP4 also promotes MARK pathway activation and induces the cancer stem cell-like phenotype of TNBC24." (PMID 27604655, 2016). "Consistent with our in vitro data, analysis of tissue microarrays and RNA sequencing expression data from The Cancer Genome Atlas (TCGA) revealed a wide distribution of DUSP4 expression in pan-negative samples and an inverse relationship between DUSP4 and EGFR expression." (PMID 26084293, 2015). "Thus, DUSP4-modulating agents aimed at increasing its expression may provide new therapeutic options for the treatment of different types of cancer, including PDAC, GC, HNSCC, and BC." (PMID 40943262, 2025). "Interestingly, when we investigated a purely NRAS-dependent murine cancer cell line, we observed a much higher baseline level of DUSP4 and DUSP6 compared to its dual NRAS and AKT-addicted counterpart, which is suggestive of a certain exclusivity towards the RAS oncogenic pathway." (PMID 37946160, 2023). "Therefore, many studies on dysregulated DUSP4 expression and cancer have been performed." (PMID 34679636, 2021). "However, contradictory roles have been reported for DUSP4 in cancer." (PMID 29212207, 2017). "Interestingly, DUSP4 has been related to drug resistance in several cancers." (PMID 29212207, 2017). "While several reports have revealed that DUSP4 may play a role in promoting cancer progression." (PMID 25688264, 2015).
cancer (continued). "In Ras/MAPK mutant cancers, a conserved gene signature that includes ETV4/5, SPRY2/4, DUSP4/6, and EPHA2/4 is a reliable biomarker of pathway activation and is associated with good clinical response to MEK inhibitor therapy." (PMID 41446112, 2025). "In line with the heterogeneous expression of DUSP4 among different subsets of cancer cells in KRASG12C‐mutant LUAD samples, we also observed varied basal expression of DUSP4 in a panel of KRASG12C‐mutant LUAD cell lines." (PMID 41025426, 2025). "Thus, targeting MEK1/2 and DUSP4/16 may provide a more effective approach for cancer therapy." (PMID 40339685, 2025). "Early evidence of the involvement of DUSP4 in cancer was provided by Yip and colleagues, who showed that PDAC cells expressing oncogenic KRAS upregulates the expression of DUSP4 to counteract ERK1/2 pathway activation." (PMID 40943262, 2025). "DUSP4 is one of the most closely related enzymes of the well characterized DUSP1, and its role in cancer progression gained importance in the last decade." (PMID 40943262, 2025). "In contrast, dual inactivation of DUSP4 and DUSP6 selectively impairs growth in NRAS and BRAF mutant cells in cancer through hyperactivation of MAPK signaling." (PMID 37026010, 2023). "Their concurrent upregulation was particularly interesting, since a recent report had suggested a digenic dependence on DUSP4 and DUSP6 in MAPK-driven cancers." (PMID 37946160, 2023). "NanoString® gene expression analysis of preneoplastic and tumorous tissue revealed a gradual overexpression of the cancer stem cell marker CD133 and Dual Specificity Phosphatases 4 and 6 (DUSP4/6)." (PMID 37946160, 2023). "Active RAS/MAPK signaling in cancer cells induces the expression of negative regulators of the RAS/MAPK pathway, such as MAPK phosphatases (e.g., DUSP4) and Sprouty (Spry) proteins." (PMID 37842094, 2023). "We therefore combined PHLDA1, DUSP4, and EPHA2 genes into an optimized signature henceforth referred to as “Carcinoma of the Ovary MEK/ERK Signature” (COMS)." (PMID 36362153, 2022). "DUSP4 inactivates MAPKs (ERK, p38 and JNK) by dephosphorylating them in cell lines 15, thus exerting an important role in cell physiology and pathological processes, such as cell growth, cellular senescence, stress‐induced apoptosis and cancers." (PMID 27957827, 2017). "Together, these data indicate that the DUSP4/16 mediated ERK-JNK crosstalk is conserved between cell lines (epithelial, fibroblast, immune, and cancer cells) based on which the dynamic model features ERK induced mRNA and protein expression of DUSP4/16 that catalyze the dephosphorylation of JNK." (PMID 23060802, 2012). "Moreover, DUSP4 expression was significantly correlated with the infiltration levels of CD4+ T cells, CD8+ T cells, B cells, neutrophils, and dendritic cells in various cancer types." (PMID 35774798, 2022). "Although there are no trials targeting DUSP4, siRNA depletion of DUSP4 sensitizes cancer cell lines to drugs to which they were otherwise resistant, a strategy that may be of value in mUM." (PMID 33008022, 2020). "The fact that DUSP4 may not commonly be overexpressed in primary UM may suggest that its enhanced expression is specific for mUM, as in other cancers; however, this requires further investigation." (PMID 33008022, 2020). "Regardless, both DUSP4 and TRIM3 on opposite sides of our 9-gene ratio are suppressors of metastasis of hepatic cancer, suggesting tissue-specific if not pan-cancer roles in survival." (PMID 34007962, 2021). "RTK-activated cancers, unlike BRAF V600E-activated cancers, may harbor lower levels of the ERK1/2 phosphatase, DUSP4." (PMID 26084293, 2015).
infection (22 papers, 2010 to 2025). The state of being infected such as from the introduction of a foreign agent such as serum, vaccine, antigenic substance or organism. "DUSP4 deficiency in mice limited the Th1 immune response and increased the susceptibility to infection with the protozoan Leishmania mexicana." (PMID 31159473, 2019). "DUSP4-deficient mice were protected from the excessive inflammatory response during septic infection." (PMID 21547253, 2011). "In vivo, PSC infection caused severe bone destruction, which was mitigated by DUSP4 overexpression." (PMID 40177487, 2025). "Observations in DUSP4 KO mice have demonstrated the critical role of DUSP4 in the inflammatory response to infection." (PMID 36152748, 2022). "Using a novel DUSP-4 deletion mouse model we have demonstrated a key role for MKP-2 in regulating infection mediated by either Leishmania mexicana, Leishmania donovani, or Toxoplasma gondii." (PMID 31336892, 2019). "Additionally, the osteoclast marker protein CTSK was upregulated following infection but returned to baseline levels after DUSP4 overexpression, indicating a protective effect against infection-induced bone resorption." (PMID 40177487, 2025). "Expression of DUSP1 and DUSP4 was unaltered by infection with RV1B." (PMID 30333178, 2019). "Following infection with the intracellular parasite Leishmania Mexicana, mice lacking DUSP4/MKP-2 were found to be more susceptible to infection, with an increased parasite burden and lesion size and this was accompanied by a suppression of Th1 and/or increased Th2 responses." (PMID 30401534, 2019). "Parasitic infection suppresses DUSP4 expression, relieving its negative regulation of the MAPK pathway and leading to excessive osteoclast differentiation." (PMID 40177487, 2025).
metabolic disease (4 papers, 2015 to 2026). A congenital disorder (due to inherited enzyme abnormality) or acquired (due to failure of a metabolically important organ) disorder resulting from an abnormal metabolic process. "Moreover, deficiency of 10 DUSPs, as well as induction of DUSP4 are associated with metabolic diseases." (PMID 42087139, 2026).
bacterial infections (1 paper, 2024). "Upregulation of GJB2, VNN1, DUSP4, SerpinB7, and IL10, and downregulation of PKMYT1, S100A4, GGTA1P, and SLC22A31 were most strongly associated with bacterial infection." (PMID 39395995, 2024).
DUSP4 also shares sentences with these, for which no sentence is quoted: experimental autoimmune encephalomyelitis (2 papers); leukemia (2); parasite infection (2); rectal cancer (2); thyroid cancer (2); viral infections (2); acute kidney injury (1); adenocarcinoma (1); Arthritis (1); atrial fibrillation (1); cardiac hypertrophy (1); cervical cancer (1); COVID-19 (1); cutaneous leishmaniasis (1); delirium (1); dementia (1); dry eye (1); Erythema (1); esophageal squamous cell carcinoma (1); fatty liver disease (1); fibrosarcoma (1); Hepatic steatosis (1); Hypercholesterolemia (1); Hyperglycemia (1); Hyperinsulinemia (1); hypertriglyceridemia (1); influenza (1); kidney disease (1); laryngeal carcinoma (1); malignant glioma (1).
A further 27 diseases each share a sentence with DUSP4 in 1 paper.